COL4A5 (collagen type IV alpha 5 chain)
Diseases named in the same sentence as COL4A5 in open-access papers (continued):
Sharing a sentence is not in itself a finding about the gene and the disease.
retinal degeneration (1 paper, 2020). Degeneration of the retina. "However, we cannot rule out the possibility that night vision problems, retinal degeneration, or balance areflexia might develop as these children age.Finally, in family HL16 with an X-linked HL inheritance pattern, we found a novel hemizygous missense variant p.(Tyr30Cys) of COL4A5." (PMID 32842620, 2020).
kidney disease (59 papers, 2012 to 2026). "The presence of COL4As (COL4A3, COL4A4, COL4A5) gene variants and other genetic variants associated with kidney disease was examined using a comprehensive gene panel." (PMID 40753325, 2025). "Variations in the genes that encode these α chains—especially COL4A1, COL4A3, COL4A4, and COL4A5—have been associated with several kidney disorders, which involve not only glomerular dysfunction but also the formation of cysts." (PMID 40565535, 2025). "Seven of these patients had family histories of kidney disease, and all patients exhibited an X-linked dominant mode of inheritance of COL4A5 variants." (PMID 39625990, 2024). "X‐linked Alport syndrome (XLAS) is an inherited renal disease caused by rare variants of COL4A5 on chromosome Xq22." (PMID 38400605, 2024). "A heterozygous variant in the COL4A3/A4 is associated with a different risk of developing severe kidney disease compared to a hemizygous one in males or even a heterozygous change in the COL4A5 gene in females." (PMID 36553470, 2022). "This study explored novel deletion and missense mutations in COL4A5 responsible for renal disorder in two Han Chinese families." (PMID 33748275, 2021). "All other family members presented only the COL4A5 mutation, and their clinical courses were consistent with benign hematuria (in females) and slowly progressing renal disease (in males)." (PMID 30691124, 2019). "WES identified 2 novel and 2 known pathogenic COL4A3/COL4A4/COL4A5 mutations in 3 families with previously unexplained inherited kidney disease." (PMID 25381091, 2014). "Two Col4a5 truncation mutations have been identified in dogs (Samoyed and Navasota dogs) with clinical features of proteinuria and progressive kidney disease leading to terminal failure." (PMID 25110662, 2014). "In our study, the c.4298–8G > A variant was a non-truncating mutation, and the proband’s two maternal uncles, who may have carried the COL4A5 mutation, died of kidney disease at the ages of 24 and 10, respectively." (PMID 38671472, 2024). "huPTC from a healthy donor and patients with a hereditary kidney disease other than AS showed strong expression of COL4A5 mRNA measured by quantitative PCR, as seen in human kidney tissue." (PMID 41531438, 2026). "The penetrance of hematuria in COL4A5 is high in both males and females, especially in males with kidney disease." (PMID 39981328, 2025). "Alport kidney disease (AKD) is a spectrum of kidney disorders caused by pathogenic variants in the α3, α4, and α5 chains of collagen type IV, which are translated from the COL4A3, COL4A4, and COL4A5 genes, respectively." (PMID 39907758, 2025). "For instance, Col4a3 knockout mice on the 129/Sv background typically develop end-stage renal disease more rapidly than Col4a5 G5X mice on the C57BL/6.Cg background." (PMID 41290692, 2025). "In this kindred, the coinheritance of COL4A5 mutations and homozygous MYO1E variants were associated with more severe kidney disease within a family initially recognized to have XLAS." (PMID 25739341, 2015). "XLAS patients, especially males whose single copy of the COL4A5 gene is disrupted, suffer from a life-threatening renal disease, the mechanism of which remains unclear." (PMID 40075271, 2025). "This is the case of a family with XLAS, in which the coinheritance of COL4A5 mutations and homozygous MYO1E variants were associated with more severe kidney disease, and can explain a highly variable renal phenotype, inexplicable by conventional pedigree analysis." (PMID 29089023, 2017). "Type IV collagen-related nephropathies are a genetically diverse group of inherited kidney disorders caused by mutations in the collagen type IV alpha-3 (COL4A3), alpha-4 (COL4A4) or alpha-5 (COL4A5) genes, which encode essential components of the glomerular basement membrane (GBM)." (PMID 41562995, 2025). "The five genes COL4A5, COQ8B, NPHP1, PAX2, and WT1 accounted for 66.9% of the monogenetic kidney disease diagnoses." (PMID 39363361, 2024).
kidney disease (continued). "Predicted pathogenic variants of the COL4A5 gene were established in one out of 2320 individuals, and COL4A3 and COL4A4 variants in one in 106 individuals in populations without kidney disease." (PMID 36982595, 2023). "In the patient with typical extrarenal features and GBM lamellation (index of family 11), whole exome sequencing using a kidney disorders gene panel identified COL4A4 variant c.2690G>A (p.Gly897Glu), but no additional variants in COL4A3/COL4A4/COL4A5 or other podocyte-related genes." (PMID 36925663, 2023).
tumor (25 papers, 2009 to 2025). "The SLC31A2 and COL4A5 genes were identified to be associated with tumor resistance to most chemotherapies." (PMID 36513682, 2022). "The EPHA2, ITGB4, and COL4A5 genes have been associated with tumor progression by exhibiting cell invasion and metastasis." (PMID 34299042, 2021). "Similarly, several genes encoding proteins involved in tumor shedding, adhesion and migration, such as collagens (COL4A5, COL4A6), integrins (ITGB4) and laminins (LAMA3), were overexpressed and positively associated with pathogenic bacteria in OSCC tumor microenvironment." (PMID 38589501, 2024). "Consistent with our cell culture data, Col4A5 was significantly upregulated in the lungs of tumor-bearing mice, especially in the lungs of mice with large tumor sizes." (PMID 37903851, 2023). "Correlation among the 9 down-regulated collagen genes in GC tumor was also analyzed, and the results showed that a strong positive correlation existed between the mRNA expression of COL4A5 and COL4A6." (PMID 36596829, 2023). "Through the data mining of a microarray dataset composed of matched tumor-normal tissues from forty OSCC patients, we distilled overexpressed genes statistically associated with angiolymphatic invasion, including DDR1, COL4A5, COL4A6 and PDPN." (PMID 32244515, 2020). "Recent evidence indicated that COL4A5 played an important role in tumor progression." (PMID 38023248, 2023). "But it is still puzzling why the expression of COL4A5 is down-regulated in GC tumor tissues." (PMID 36596829, 2023). "Recently, the specific expression of COL4A5 in the tumor microenvironment has been reported." (PMID 34440281, 2021). "As the tumor progressed, COL4A1, COL4A2 and COL4A6 expression gradually increased, and COL4A3, COL4A4 and COL4A5 gradually decreased." (PMID 40351420, 2025). "Among these proteins, expression levels of Col4A5, GPC1 and HAS2 increased progressively with metastatic potential or tumor size in cell and animal experiments, respectively." (PMID 37903851, 2023). "Our volcano plot and GO analysis showed the significant downregulation of tumor-suppressive genes, such as ANOS1, CDH11, COL4A5, POSTN, PTN, and BEX1 in As- transformed cells, which is considered an early event of carcinogenesis." (PMID 35954277, 2022). "In our NCKU-OrCA-40TN cohort, we noticed that five collagen subunits are upregulated genes in the tumor tissues compared to that in the normal counterparts, including COL1A1 (3.5×), COL4A1 (2.1×), COL4A2 (3.3×), COL4A5 (5.6×), and COL4A6 (9.2×)." (PMID 32244515, 2020). "Among these, COL4A5 and COL4A6 were each statistically co-overexpressed with DDR1 in the 40 tumor tissues." (PMID 32244515, 2020). "In contrast, the variation of COL4A3, COL4A4 and COL4A5 expression between tumor and normal tissues were lacking of significance, and presented an inconsistent tendency in three databases." (PMID 40351420, 2025). "The mRNA expression level of all six type IV collagen genes (COL4A1, COL4A2 COL4A3, COL4A4, COL4A5 and COL4A6) was higher in metastatic tissue compared to primary tumor tissue, although being significant only for COL4A3 (p = 0.013) and COLA4A4 (p = 0.005) genes." (PMID 35693557, 2022). "Since the expression of COL4A5 is decreased in GC tumor tissue and a strong positive correlation exists between expression of COL4A5 and COL4A6, the formation and quantity of minor type IV collagens in GC tumor might be affected." (PMID 36596829, 2023). "However, in this case one gene (Col4a5), functions as a hotspot for retroviral integrations that induce expression of another distal gene (Irs4), without affecting the expression of Col4a5 itself in any tumor analyzed (and data not shown)." (PMID 24886479, 2014). "On the other hand, Col4a1, Col4a3, Col4a5, Col5a3, Col11a2, Col14a1, Col15a1, Col16a1, and Col22a1 were found in normal ECM but not in tumor ECM; Col25a1 was found only in tumor ECM but not in normal ECM." (PMID 36547361, 2022).
cancer (19 papers, 2012 to 2025). A tumor composed of atypical neoplastic, often pleomorphic cells that invade other tissues. "The COL4A5 gene encodes one of the Type IV collagen components that also plays a crucial role in angiogenesis, tissue remodeling, and cancer progression." (PMID 34299042, 2021). "Col4a5 is linked to several cancers while Plaur is a regulator of tissue reorganisation." (PMID 22260314, 2012). "Xiao’s research showed that COL4A5 could promote the progression of cancer by the discoidin domain receptor-1, thus, COL4A5 was a risk factor in our model." (PMID 36186476, 2022). "Notably, transcriptional loss of Col4a5 and Col4a6 in the epithelial basement membrane was observed in CRC and during cancer cell invasion." (PMID 29339782, 2018). "Those pathways specifically altered in primary tumors were associated with an abnormally increased expression of genes that are involved in focal adhesion (e.g., PRKCA, CRK, and BCL2), PI3K-Akt signaling (e.g., PHLPP2, PRKCA, PPP2R3A and KIT) and cancer pathways (e.g., COL4A5, LAMC1 and BCL2L1)." (PMID 27662660, 2016). "Overexpression of COL4A5 may play a role in the ECM in cancer." (PMID 40362431, 2025). "Notably, loss of Col4a5 and Col4a6 chains in CRC tissues have been suggested to be related to the observation that cancer cells break through the epithelial basement membrane during the early stages of cancer cell invasion." (PMID 29339782, 2018).
genetic disorder (10 papers, 2021 to 2025). "PP4: The clinical manifestations were remarkably in line with a genetic disorder resulting from an abnormality in the COL4A5 gene." (PMID 38671472, 2024). "This is the first report of the novel c.385–716G > A splicing mutation in the COL4A5 gene, which illustrates the importance of performing WGS to find additional mutations in WES-negative patients with highly suspected forms of genetic diseases." (PMID 36714647, 2022). "AS is a rare genetic disorder that caused by pathogenic variants in COL4A3, COL4A4, and COL4A5 that result in abnormalities of the collagen IV α345 network of basement membranes." (PMID 34774011, 2021). "The authors concluded that the phenotype was a consequence of the two distinct genetic disorders, rather than one mutation enhancing the other, pleading for a digenic inheritance of COL4A5 and MYO1E variants in this case." (PMID 40003707, 2025). "However, currently, gene therapy is not a proven treatment option for genetic diseases, but initial results in treating both AS podocyte-lineage cell lines and COL4A5 truncating variants have shown promise." (PMID 36119140, 2022).
infection (6 papers, 2010 to 2025). The state of being infected such as from the introduction of a foreign agent such as serum, vaccine, antigenic substance or organism. "In contrast, genes associated with ECM organization (Col4a5, Col4a6, Col6a4), microtubule polymerization formation (Tppp, Tppp3), and mitochondrial biogenesis (Ppargc1a) were found to be among the top down-regulated DEGs during infection." (PMID 29339782, 2018). "Two days after infection, Col4a5 mRNA levels were analyzed by qRT-PCR." (PMID 41417821, 2025). "For instance, P4 of our cohort, who had a missense mutation of COL4A5 inherited from her mother, presented with macroscopic hematuria during infection, and she did not suffer from any hearing loss or visual problem." (PMID 32703181, 2020).
COL4A5 also shares sentences with these, for which no sentence is quoted: X-linked Alport syndrome (62 papers); renal failure (12); autosomal recessive Alport syndrome (6); glomerulopathy (4); melanoma (4); Hearing impairment (3); macular holes (3); sensorineural hearing loss (3); Uterine leiomyoma (3); Andersen-Tawil syndrome (2); autosomal dominant Alport syndrome (2); diabetes (2); Fabry disease (2); nail-patella syndrome (2); Ventricular arrhythmia (2); acute lymphoid leukemias (1); adenocarcinoma (1); Adult onset (1); Alstrom syndrome (1); amyotrophic lateral sclerosis (1); aneurysm (1); aniridia (1); Arrhythmia (1); autosomal recessive disease (1); basal cell carcinoma (1); Basement membrane disease (1); biotinidase deficiency (1); breast tumors (1); bronchiolitis obliterans syndrome (1); cataract (1).
A further 61 diseases each share a sentence with COL4A5 in 1 paper.